DYRK1A (dual specificity tyrosine phosphorylation regulated kinase 1A)
Diseases named in the same sentence as DYRK1A in open-access papers (continued):
Sharing a sentence is not in itself a finding about the gene and the disease.
infection (10 papers, 2011 to 2025). The state of being infected such as from the introduction of a foreign agent such as serum, vaccine, antigenic substance or organism. "Furthermore, DYRK1A could play a broader role in virus-host cell interaction beyond the cell cycle effects, since it has been shown to influence the infection by pathogenic human coronaviruses, HIV and human cytomegalovirus (HCMV)." (PMID 37900285, 2023). "Our review should provide useful guidance for the research community and will hopefully inspire new projects aiming at better understanding the implications of DYRK1A in hematologic homeostasis, inflammation and infection." (PMID 40519271, 2025). "The nuclear localization mutant DYRK1A also restored infection, possibly due to residual DYRK1A in the nucleus." (PMID 37310920, 2023). "Consistent with protein expression data, WT and kinase-dead constructs significantly rescued infection in DYRK1A KO cells." (PMID 37310920, 2023). "Next, we used macrophage-tropic replication-competent HIV-1 (BaL-3) to determine if DYRK1A would have the same effect with multiple rounds of infection." (PMID 31852782, 2020). "Activated PBMCs were infected with a VSV-G pseudotyped HIV-1 luciferase reporter virus and 24-hours after infection different concentrations of the DYRK1A inhibitor INDY were added to the culture medium." (PMID 26641855, 2015). "Additionally, these authors validated the proviral roles of DYRK1A in mouse hepatitis virus, porcine deltacoronavirus, and porcine sapelovirus, demonstrating that DYRK1A is an essential host factor for infections by multiple viruses." (PMID 40519271, 2025). "To confirm DYRK1A complementation could rescue infection with authentic virus, we challenged these cell lines with the icSARS-CoV-2-mNG reporter virus or WT SARS-CoV-2 WA/01/2020 to assess viral replication by mNG production and by plaque assay, respectively." (PMID 37310920, 2023). "However it is interesting to note that in some of these infections with lower incidence in people with DS population, DYRK1A plays antiviral functions (e.g., HIV-1 and HPV), whereas in those that are more frequent or severe in this group (such as SARS-CoV-2), DYRK1A exerts proviral activities." (PMID 40519271, 2025). "Furthermore, studies using mouse genetic models found that Dyrk1a plays an important role in mature B-cell function in response to infection or vaccination by regulation of class-switch recombination mediated by phosphorylation of mutS homolog 6 (MSH6) protein." (PMID 37900285, 2023). "In a previous study, we showed that the AD169 and Merlin infection of TEV-1 cells resulted in cellular re-localization and accumulation of DYRK1A and DYRK1B." (PMID 38932210, 2024). "Knockdown or pharmacological inhibition of DYRK1A had pronounced effects on HIV replication in macrophages compared to dividing cells, even with multiple rounds of infection." (PMID 31852782, 2020). "The results showed that DYRK1A, FAM135A, PLAG1, ZNF148, and PHC3 were obviously inhibited at infection times of 3 h, 6 h, and 9 h pi." (PMID 31784561, 2019). "Using infection of human cerebral organoids to assess protein changes, we show CMV infection dysregulates localisation and expression of DYRK pathway (DYRK1A, DYRK1B) and SHH pathway (Shh morphogen, Gli2 transactivator, ULK3 kinase, and Rb tumor suppressor protein) proteins." (PMID 38504123, 2024). "Of note, DYRK1A-K188R was not as effective at restoring icSARS-CoV-2-mNG infection relative to DYRK1A-Y321F." (PMID 37310920, 2023). "Downregulation of 4 miRNA target genes, including PLAG1, ZNF148, PHC3, and DYRK1A, was first found in CVB3-infected cells, though 4 genes were associated with nonenterovirus replication and infection." (PMID 31784561, 2019).
heart disease (2 papers, 2012 to 2025). "Although the biological relationship between B4GALNT2 and human heart diseases has yet to be documented, AKAP7, DYRK1A and FAM19A2 have all been implicated in its etiology." (PMID 23176082, 2012). "The results of this trial, in conjunction with our results using LCTB-92 in a preclinical animal model of MI, are encouraging in that the inhibition of DYRK1A may represent a new first-in-class therapy to treat heart disease." (PMID 40901489, 2025).
hematologic disorder (2 papers, 2023). A disease involving the hematopoietic system. "Dyrk1A would be one of the proteins involved in hematologic disorders of DS patients, but other proteins linked with DS aneuploidy could be involved." (PMID 37415307, 2023).
DYRK1A also shares sentences with these, for which no sentence is quoted: type 2 diabetes (4 papers); lymphoma (3); metabolic disease (3); allergies (2); anemia (2); cardiovascular disease (2); cognitive disorder (2); genetic disorders (2); Glucose intolerance (2); Hyperglycemia (2); knee osteoarthritis (2); myeloid leukemia (2); Parkinson (2); Pick disease (2); Strabismus (2); acne vulgaris (1); acute respiratory distress syndrome (1); adenocarcinoma (1); amyotrophic lateral sclerosis (1); Angelman syndrome (1); atherosclerosis (1); attention deficit-hyperactivity disorder (1); B cell lymphoma (1); B-cell acute lymphoblastic leukaemia (1); bipolar disorder (1); brain disorder (1); brain glioblastoma (1); cervical squamous cell carcinoma (1); chromosomal disorder (1); ciliopathy (1).
A further 46 diseases each share a sentence with DYRK1A in 1 paper.